NOX4 (NADPH oxidase 4)
Diseases named in the same sentence as NOX4 in open-access papers (continued):
Sharing a sentence is not in itself a finding about the gene and the disease.
Stroke (continued). "MTfp-NOX4 POC provides a novel insight for the treatment of stroke." (PMID 35154560, 2022). "Researches on NOX4-targeted stroke treatment have made significant progress." (PMID 35154560, 2022). "After a cerebrovascular accident, cyclooxygenases and mitochondria generate ROS due to their enzymatic activity; however, ROS generation is the principal function of the NADPH oxidase (NOXs) family NOX2 and NOX4 activity which is the major contributor of OS following a cerebrovascular accident." (PMID 35528523, 2022). "However, when treated with MTfp-siRNA, NOX4 up-regulation was reduced after stroke, where NOX4 mRNA was only 80% of the levels observed with the PBS stroke-induced control." (PMID 33869275, 2021). "Pharmacological inhibition of NOX4 could be a promising approach to develop stroke protective drugs." (PMID 31827699, 2019). "Transient upregulation of NOX4 in the cortex is also observed after endothelin-induced stroke." (PMID 32923955, 2019). "Also upregulated in the MSA frontal lobe was Nicotinamide adenine dinucleotide phosphate oxidase 4 (NOX4), which has been shown to be upregulated in neurons and endothelial cells after stroke, and its inhibition has been shown to be neuroprotective." (PMID 29850876, 2018). "While Nox2 appears to be a major source of pathological oxidative stress in the CNS, other Nox isoforms might also be of importance, e.g. Nox4 in stroke." (PMID 25617620, 2015). "Since then, this paradigm has been tested in numerous models using small molecules and Nox1-, Nox2-, and Nox4-deficient mice, resulting in different outcomes and leading to disputes whether Nox2 or Nox4 isoform is the key pharmacological target for stroke." (PMID 25617620, 2015). "In addition, it was demonstrated that Nox4 immunoreactivity was stronger in brain samples from stroke patients, providing support that these processes are also important in human stroke." (PMID 24961415, 2013). "Indeed these authors showed significant evidence to suggest that although VAS2870 is non-selective for the Nox isoforms, it was effective in attenuating a Nox4 driven progression of injury in the early hours of stroke." (PMID 24961415, 2013). "We have previously characterized the temporal and cellular expression of NADPH oxidase subunits, Nox2 and Nox4, concurrently with increased superoxide generation and progression of damage in the acute phase of stroke and reperfusion in conscious rats (up to 7 days)." (PMID 24961316, 2013). "In addition to this NOX4 KO study, another group recently showed first results confirming the detrimental role of NOX4 post stroke." (PMID 22625431, 2012). "NOX4 mRNA was upregulated 6 h post-stroke and then returned to control levels." (PMID 22625431, 2012). "Nox4 may play an important role in ischemia/reperfusion-induced neoangiogenesis during stroke recovery." (PMID 22146586, 2011). "Restoration of oxidative stress reversed the stroke-protective phenotype in Nox4−/− mice." (PMID 20877715, 2010). "Furthermore, NOX4 is a culprit in CNS disease besides stroke and therefore this POC may have utility in other brain pathologies." (PMID 33869275, 2021). "Importantly, post-stroke treatment with the putative NOX inhibitor VAS2870 improved recovery, suggesting that NOX4 may be a viable therapeutic target in the setting of stroke." (PMID 32923955, 2019). "Indeed Nox4 is reported to be increased in neurons following both experimental and clinical stroke and to be an important regulator of focal ischaemic stroke in the mouse; it may contribute to ROS generation and lesion progression in the current study." (PMID 25375101, 2014). "Angiogenic blood vessels 3 and 7 days post-stroke were observed to co-localise with both Nox2 antibody and dihydroethidium fluorescence suggesting a role for Nox2 generated superoxide during the phase of vascular remodeling, whilst Nox4 expression was detected once new cerebral vessels had formed." (PMID 24961316, 2013).
Stroke (continued). "Finally, we wanted to examine whether these genetic insights into the biology of oxidative stress in stroke and the role of NOX4 in general can be translated into a therapeutic intervention." (PMID 20877715, 2010). "Additionally, NOX4's expression had been shown to increase when stroke is induced in rats." (PMID 20877473, 2010). "Importantly, NOX4 staining was also stronger in brain samples from stroke patients." (PMID 20877715, 2010). "The outcomes were measured between 24 h and 4 weeks post-stroke, focusing on the roles of NOX1, NOX2, and NOX4 in the recovery process." (PMID 39334724, 2024). "This trend is seen in experiments, conducted by a different operators, in animals induced with stroke after being treated with PBS, NOX4 siRNA alone or MTfp-scramRNA control." (PMID 33869275, 2021). "In the present study, we demonstrated that NOX4 and apoptosis pathway mediated the protective effects of SCM-198 on endothelial cells and neurons during stroke in vivo and in vitro." (PMID 31827699, 2019). "NOX4 has been shown to be upregulated and co-localized with TLR4, after cerebral ischemia and reperfusion in mice and in brain tissue of human stroke patients." (PMID 26030867, 2015). "Expression levels of Nox4 are increased in a number of diseases including fibrosis, PAH and stroke, but the functional role ascribed to Nox4 is frequently both deleterious and beneficial." (PMID 23125837, 2012). "To establish any potential specificity of this function for NOX4 compared to NOX1 and NOX2 in stroke, we carried out identical experiments in 6- to 8-wk-old Nox1y/− and Nox2y/− mice." (PMID 20877715, 2010). "Therefore, we hypothesized that NOX4 is the most relevant source of ROS in stroke." (PMID 20877715, 2010). "This study has limitations in that it is difficult to fully understand the role of NOX4 reduction in stroke recovery without ROS monitoring and long-term recovery outcome observations." (PMID 39334724, 2024). "In this proof-of-concept study, we chose to administer treatment (MTfp-siRNA, MTfp-scramRNA, NOX4 siRNA alone, and PBS controls) prior to stroke induction to demonstrate delivery across the intact BBB since the integrity will certainly be compromised by the invasive nature of stroke induction." (PMID 33869275, 2021). "Deletion of the NOX4-coding gene in mice, as well as inhibiting the ROS-generating activity of NOX with a pharmacological inhibitor, reduces brain damage and improves neurological function, even when given hours after a stroke." (PMID 20877715, 2010). "Strictly adhering to current expert recommendations for basic stroke trials, we here demonstrate that in the absence of NOX4, brain tissue can be salvaged after ischemia or reperfusion injury (as occurs in the tMCAO model)." (PMID 20877715, 2010). "Most notably, continuous assessment of functional deficits until 7 d after stroke revealed that Nox4-null mice indeed showed a better amplitude rather than simply altered kinetics of recovery." (PMID 20877715, 2010). "Clearly, elimination of NOX4 remains beneficial in the absence of arterial recanalization, a condition frequently observed in human stroke." (PMID 20877715, 2010). "Serial magnetic resonance imaging of living mice up to 6 d after stroke showed that in Nox4−/− mice the infarct volume did not increase over time, thus indicating that deletion of the Nox4 gene provides sustained protection against stroke." (PMID 20877715, 2010). "Again, post-stroke application of VAS2870 to Nox4−/− mice had no additive neuroprotective or superoxide-lowering effect compared to the outcomes in wild-type animals treated with VAS2870 or untreated Nox4−/− mice." (PMID 20877715, 2010). "Therefore, we had to exclude systemic vascular effects of NOX4 deletion on blood pressure, which may affect stroke outcome independent of a specific neuronal or neurovascular mechanism." (PMID 20877715, 2010).
Stroke (continued). "VAS2870 did not display an additional protective effect in NOX4 knockout mice, whereas it did so in WT mice, further suggesting that NOX1 and 2 have no major implication in stroke pathology." (PMID 22625431, 2012).
lung cancer (36 papers, 2015 to 2025). A malignant neoplasm involving the lung. "High levels of NOX4/ROS are associated with enhanced motility/migration in lung cancer cells." (PMID 35860704, 2022). "In pleural mesothelial cells treated with heat-killed M. tuberculosis, both cell migration and the invasion of lung cancer cells via NOX4 signaling have been demonstrated." (PMID 39337604, 2024). "For example, EFHD2 promotes lung cancer cell resistance to chemotherapy through the NOX4-ROS-ABCC1 signaling, and high level of EFHD2 is correlated with a worse survival in lung cancer patients received chemotherapy." (PMID 39308671, 2024). "Halimu and colleagues revealed that the epithelial-to-mesenchymal transition (EMT) and overall cell migration were induced in A549 lung carcinoma cells by PS nano- and microplastics via the upregulation of ROS production and NADPH oxidase 4 expression." (PMID 39449700, 2024). "In lung cancer, for example, increased expression of NADPH oxidase 4 (NOX4) by IL-6 which is an inflammatory cytokine induces ROS production." (PMID 37168992, 2023). "In gastric and lung cancer cells, ROS production due to the upregulated NADPH oxidase 4 (NOX4) was confirmed to promote AR and metastasis through EGFR signaling." (PMID 38144298, 2023). "NOX4 is upregulated in a variety of type cancers, and in lung cancer, tumoral NOX4 recruits TAMs via ROS/phosphatidylinositol 3-kinase signaling-dependent various cytokine production, a process that contributes to cancer malignant progression." (PMID 37891977, 2023). "It was recently found that NADPH oxidase 4 (NOX4), Spi-B, Krüppel like factor 6 splice variant 1 (KLF6-SV1), and CCL7 are highly expressed in lung cancer cells." (PMID 38022518, 2023). "Mice with BCG pleura infection showed induced expression of NOX4 and increased tumorigenic potential of lung cancer compared with mice injected with PBS." (PMID 35525982, 2022). "In the lungs, NADPH oxidase 4 (nicotinamide adenine dinucleotide phosphate-oxidase 4, NOX4) has been studied mainly because of its association with lung cancer." (PMID 35346198, 2022). "ROS-induced EMT has been reported to be NOX4-dependent in human metastatic breast epithelial cells and in lung cancer cells." (PMID 36359304, 2022). "In recent studies, ROS generation induced by NOX4 has been involved in anoikis resistance of gastric and lung cancer cells." (PMID 36359304, 2022). "NOX4–autophagy signaling axis contributes to the interaction between tuberculosis fibrosis and lung cancer." (PMID 33567693, 2021). "A Mycobacterium bovis bacillus Calmette–Guérin (BCG)-induced pleurisy mouse model was used to explore the role of NOX4 in tuberculous pleurisy-assisted metastatic potential of lung cancer." (PMID 33567693, 2021). "Consistent with this, NOX4 silencing increased autophagic flux and decreased the migration and invasiveness of lung cancer cells." (PMID 33567693, 2021). "Wound healing assays showed that conditioned medium of mouse PMCs after HKMT treatment increased lung cancer cell migration, whereas suppression of NOX4 significantly inhibited lung cancer cell migration." (PMID 33567693, 2021). "We assessed the effects of downregulating NOX4 signaling on tuberculous effusion-treated A549 cells in regulation of autophagy signaling and invasiveness of lung cancer." (PMID 33567693, 2021). "In humans, TPE has been shown to exhibit higher NOX4 levels compared to transudate and to increase migration and invasiveness of lung cancer cells." (PMID 33567693, 2021). "Mice with Mycobacterium bovis bacillus Calmette–Guérin (BCG) pleural infection exhibited increased expression of NOX4 and enhanced malignant potential of lung cancer compared to mice with intrathoracic injection of phosphate-buffered saline." (PMID 33567693, 2021). "Downregulating NOX4 signaling reduced the infiltration of lung cancer cells and the expression of proinflammatory cytokines with restoration of autophagosomes in lung tissues." (PMID 33567693, 2021).
lung cancer (continued). "We found that apatinib significantly increased NOX4 expression, which suggested that NOX4 participated in apatinib-induced ROS production in lung cancer cells." (PMID 33980809, 2021). "Our results showed that lung cancer cells enhanced the NOX4 expression and invasive potential after exposure to the conditioned medium of heat-killed Mycobacterium tuberculosis stimulated mesothelial cells or tuberculous pleural effusion." (PMID 33567693, 2021). "Inhibiting the function or expression of NOX4 via pharmacologic inhibitors or RNAi strategy significantly blocks lung cancer progression." (PMID 34277453, 2021). "NADPH oxidase 4 (NOX4)-overexpressed lung cancer cell lines A549 and Calu-1, induced the recruitment of murine M2-like TAMs via the ROS/PI3K signaling-dependent pathway." (PMID 32486098, 2020). "As a previous study indicated that JAK1 is the critical JAK kinase contributing to STAT3 activation and mediates IL-6-induced STAT3 activation in lung cancer cells, we next determined the effect of NOX4 overexpression on JAK1/STAT3 activity in A549 cells." (PMID 25504436, 2015). "The NOX4 knock-out (KO) mice showed reduced tuberculosis fibrosis and the potential to promote lung cancer metastasis, which indicates that the NOX4 signaling axis regulated by tuberculous fibrosis may lead to enhanced tumorigenic potential." (PMID 35525982, 2022). "The BCG+ KLN205 (KLN205 cancer cell injection after BCG treatment) NOX4 KO mice group showed reduced tuberculous fibrosis-promoted metastatic potential of lung cancer, increased autophagy, and decreased expression of TGF-β, IL-6, and TNF-α compared to the BCG+KLN205 WT mice group." (PMID 33567693, 2021). "The role of NOX4 on the metastatic potential of lung cancer cells was investigated." (PMID 33567693, 2021). "BCG increased the metastatic potential of lung cancer cells in a NOX4-dependent manner." (PMID 33567693, 2021). "Furthermore, some studies have reported that NOX4 signaling reinforces the growth and invasion of lung cancer via positive feedback regulation of PI3K/Akt signaling." (PMID 33567693, 2021). "This led us to hypothesize that NOX4 may be a link between tuberculous fibrosis and lung cancer." (PMID 33567693, 2021). "Thus, we evaluated whether tuberculous fibrosis promotes the malignant potential of lung cancer and whether NOX4 regulates the cellular interaction between PMCs and lung cancer cells." (PMID 33567693, 2021). "Moreover, one isoform, NOX4, is predominantly overexpressed and hyperactivated in lung cancer." (PMID 34277453, 2021). "Our results suggest that the NOX4–autophagy axis regulated by tuberculous fibrosis could result in enhanced tumorigenic potential and that NOX4-P62 might serve as a target for tuberculous fibrosis-induced lung cancer." (PMID 33567693, 2021). "We investigated the role of NOX4 in tuberculous pleurisy-assisted tumorigenicity both in vitro and in vivo.Heat-killed Mycobacterium tuberculosis-stimulated mesothelial cells augmented the migrationand invasive potential of lung cancer cells in a NOX4-dependent manner." (PMID 33567693, 2021). "For instance, fangchinoline, by promoting the degradation of NADPH oxidase 4 to reduce cytoplasmic ROS levels, reverses EMT and inhibits the invasion and migration of lung cancer cells." (PMID 40777001, 2025). "As expected, CYB5R3 decreased the GSH/GSSG ratio and increased NOX4-dependent H2O2 production, and treatment with cell-permeable GSH-EE attenuated apoptosis mediated by CYB5R3 overexpression in lung cancer cells." (PMID 38253797, 2024). "It was demonstrated that a hydrogen peroxide-producing enzyme, NADPH oxidase 4, activates AKT to promote the growth and metastasis of lung cancer." (PMID 36826016, 2023). "We have reported that cell detachment upregulates NADPH oxidase 4 (NOX4), which maintains EGFR levels and activities that are important for anoikis resistance in human lung cancer cells." (PMID 33440835, 2021).
lung cancer (continued). "Two independent studies reported the generation of ROS as a result of the upregulation of NADPH oxidase 4 (NOX4) in gastric and lung cancer cells grown in suspension; this was observed to induce anoikis resistance and metastasis via EGFR signaling." (PMID 33854965, 2021). "While this report identified OH· as a positive modulator of lung carcinoma H460 cell migration, the present study shows that UCH-L1 induces H2O2 generation by modulating NOX4 activity and that H2O2 plays an important role in the invasion of B16F10 cells." (PMID 25915537, 2015). "Moreover, NADPH oxidase 4 (NOX4) in tumors reportedly mediates macrophage chemotaxis and M2 polarization in lung cancer by stimulating the expression of various cytokines, including CCL7, IL-8, CSF-1 and VEGF-C via ROS/PI3K/AKT signaling." (PMID 36670988, 2023). "A similar effect has been observed in lung cancer cells, where TGF-β positively regulates NOX4, inducing an increase in ROS levels mediated by the activation of NF-κB, which enhances the expression of NOX4, thereby enhancing Vimentin and Snail function and decreasing E-cadherin expression." (PMID 39696702, 2024). "Interestingly, NADPH oxidase 4 (NOX4) is normally only expressed in kidney (not one of the six cancerous tissues in the human cancer dataset) and is downregulated in various cancers but upregulated in lung cancer." (PMID 28450890, 2017).